CD4 (CD4 molecule)
Diseases named in the same sentence as CD4 in open-access papers (continued):
Sharing a sentence is not in itself a finding about the gene and the disease.
infection (continued). "The possible purgative effect of rhGH on HIV-1 from latent reservoirs may result in de novo cellular infections possibly accounting for some of the transient pattern of proliferative responses observed in virus-specific CD4+ T-cell responses." (PMID 18976455, 2008). "Such envelopes may evade neutralization by antibodies, but appear to be compromised in their interactions with CD4 and limited to infection of cells that carry high amounts of CD4 e.g. CD4+ T-cells." (PMID 18205925, 2008). "The secondary role of ICAM-1 in HIV transfer between CD4 T cells and its limited effect in 293T cells is contradictory with the more relevant role reported in the infection of CD4 T cells by free HIV particles, and the complete requirement of this molecule for transinfection induced by DC." (PMID 18377648, 2008). "Generation of activated virus-specific CD4+ HTL, which may be preferentially targeted by HIV-1, also presents the risk of de novo infection and clonal deletion." (PMID 18976455, 2008). "Taken together, our data indicate that there is sufficient antigen present within hours of infection to trigger CD4+ T cell responses, but that critical changes in the host microenvironment occur around day 2/3 post-infection that allow virus-specific CD4+ T cells to initiate their proliferation." (PMID 18404208, 2008). "This decrease may be a result of both an increased recruitment to the sites of infection as well as a drug-related decrease in the proliferative capacity of CMV specific CD4 T cells." (PMID 18982061, 2008). "Thus, the severity of bone marrow pathology during the CD4+ T cell response to unresolving FV infection appeared to be directly proportional to the relative frequency of Treg and pathogenic T cells." (PMID 19006695, 2008). "NP-2/CD4/CXCR4 cells showed a high susceptibility to AG204, AG206, AG208, HCM303, HC305, HCM308, and HCM309 isolate, while less than 1% of HIV-1 antigen-positive cells were detected after infection with HCM342, mIDU101, or mSTD104 isolates." (PMID 18577234, 2008). "However, it is possible that any infection resulting in systemic immune activation or increased peripheral blood CD4+ T cell numbers would have yielded similar results." (PMID 18648516, 2008). "Since deer mouse CD4+ T cells are not susceptible to SNV infection it is unlikely that viral proteins directly affect the LT pathways of these cells." (PMID 18976466, 2008). "Similarly, CD4+ T cells isolated from deer mice during the persistent phase of SNV infection have higher expression of Tgfβ than do CD4+ T cells isolated from deer mice during the acute phase of infection." (PMID 19043585, 2008). "A recent study, however, demonstrated that virtually all trans-infected virus could be neutralized by soluble CD4 (sCD4), a potent inhibitory protein, when it was delivered to the surface of DCs prior to trans-infection." (PMID 18725936, 2008). "We conclude from this experiment that BFFI would be protective only on the small subset of CCR5-expressing PBMC, where anchoring of the CCR5mAb allows BFFI to be in close proximity to the X4 viral fusion and prevents virus from infection and subsequent depletion of CD4 (+) T-cells." (PMID 18452606, 2008). "NuTH/I MoAb (10 μg/ml) almost completely inhibited infection of NP-2/CD4/FPRL1 cells, as well as NP-2/CD4/CCR5 cells, with all HIV/SIV strains tested, i. e., GUN-7WT, HCM342, CBL23, and mndGB-1, suggesting that FPRL1 mediates infection of HIV/SIV as a coreceptor, i. e., in a CD4-dependent manner." (PMID 18577234, 2008). "Since the expression of adhesion molecules in memory cells is higher compared to the naïve subset, the active contribution of LFA-1 to the process of HIV spread has been associated to the higher susceptibility of CD4 CD45RO T cells to HIV attachment and infection." (PMID 18377648, 2008).
infection (continued). "Virus-specific proliferation assays using 3H-thymidine incorporation were performed on WT and IL6−/− splenic CD4+ T cells, isolated either 2 weeks post infection (primary CD4+ T cell response), or at 8 weeks following a secondary infection (memory CD4+ T cell response)." (PMID 18389078, 2008). "Although the loss of the RFP marker does not identify productive infection of the target cell, it is a strong indicator of CD4-dependent entry, a prerequisite for productive trans-infection." (PMID 18725936, 2008). "To determine the effect of HCV coinfection with HIV-1 on the disease progression, we compared HIV viral loads and CD4+ T-cell counts at baseline among HIV-1 mono-infection (N = 20 cases), dual infection of HIV plus HCV (N = 135 cases) and triple infection of HIV, HCV and toxoplasma (N = 13 cases)." (PMID 19098990, 2008). "Furthermore, absolute CD4+ T-cell counts in HIV/HCV group were consistently higher than that in HIV mono-infection group (p = 0.04, 0.18, 0.03 and 0.04 for baseline, month 9, month 21 and month 33 visit, respectively)." (PMID 19098990, 2008). "Given that Langerhans cells and dermal DC do not appear to play a major role in activating CD8+ T cells during s.c. infection, we hypothesised that these subsets may be more important in driving activation of CD4+ T cells." (PMID 18301768, 2008). "14% of the virus-specific CD4+ memory T cells had responded within hours of infection." (PMID 18404208, 2008). "Within 48 hour after infection of CD4+CXCR4+ HeLa cells with the syncytium-inducing HIV-1LAI strain, a significant fraction of cells, preferentially syncytia, exhibited mitochondrial cytochrome c release, caspase-3 activation and apoptotic chromatin condensation." (PMID 18560558, 2008). "Here we show that extracellular ATP may fulfill an additional unexpected role in the defence against infection by reducing HIV-1 transmission from iDCs to CD4+ T cells." (PMID 18373845, 2008). "RANTES blocked infection of NP-2/CD4/CCR5 cells with HIV/SIV strains by 50–80%, as reported." (PMID 18577234, 2008). "To exclude the possibility that the phenotypes we observed in MHC Class I×β2M-/- and MHC Class II-/- mice were due to abnormal immune ontogeny in knockout mice, we determined the requirement for CD4 and CD8 T cells in the clearance of primary MNV infection in WT mice depleted of CD4 and CD8 T cells." (PMID 19079577, 2008). "Prime targets for microbicide attack are the virus and cellular proteins involved in the early events in infection: the entry receptors CD4, CCR5 and CXCR4, the viral envelope proteins and compounds that interfere post entry with reverse transcription and integration of HIV into the host cell." (PMID 18654624, 2008). "Three different viral proteins, Nef, Env and Vpu have evolved to ensure that cell surface CD4 is downregulated soon after entry (by the early protein Nef) and that transport of newly synthesized CD4 to the cell surface at late stages of infection is blocked (by late proteins Env and Vpu)." (PMID 18267010, 2008). "In confirmation of this, by day 7 post-infection, IL-10+ CD4+ T cells were almost exclusively CD25− indicating that, since the majority of Foxp3+ cells maintain CD25 expression during P. yoelii infection, CD25−Foxp3− CD4+ T cells are the primary source of IL-10 during both PyL and PyNL infection." (PMID 18401464, 2008). "Analysis of inhibition of pseudotype infection in the presence of anti-CD4 antibody." (PMID 18837996, 2008). "CD4+ T-cell counts in the group of dual infection (ranged from 206 to 928 cells/μl with a mean of 429 cells/ μl) was significantly higher than that in HIV mono-infection (ranged from 237 to 639 cells/ul with a mean of 390 cells/μl) (p = 0.04)." (PMID 19098990, 2008). "Since plasma viral loads remained below the level of detection at all time points, infection of such CD4+ HTL may be the result of very low levels of viral activity undetectable using current viral load assays (<50 copies/ml plasma)." (PMID 18976455, 2008).
infection (continued). "On the other hand, the follow-up study using cells expressing CD4 and wild-type CCR5 concluded that recruitment of just one CCR5 molecule by CD4-bound Env could mediate infection." (PMID 19077194, 2008). "Importantly, the additive predictive capacity of the GRGs was evident during the early stages of the infection such as when the CD4 cell count was greater than 450 cells/mm3." (PMID 18776933, 2008). "Analysis of the relative pseudotype infection in cells expressing low levels of CD4." (PMID 18837996, 2008). "Proinflammatory cytokines at 24 h post infection and reduction of CD4, CD8 and CD19 positive immune cells might make the mice immune compromised during infection." (PMID 18937835, 2008). "Likewise, CD4-independent use of CCR5 is more pronounced with virus isolates obtained shortly after infection of the macaques." (PMID 17645788, 2007). "While the degree of CD4 independence and neutralization sensitivity vary over time, the ability to productively infect monocyte-derived macrophages remains at a steady high level throughout infection." (PMID 17645788, 2007). "Interestingly, in the P/SP group of macaques there was also a fraction of animals that late in infection had a CD4-independent-HIGH and neutralization resistant phenotype." (PMID 17645788, 2007). "The interaction between ICAM-1 and LFA-1 may also play an important role in infection of CD4-positive memory T cells, which are considered a latent reservoir of the virus." (PMID 17651505, 2007). "Interestingly, the majority of virus isolates that established infection in hPBMC after infection with lysed cells were of the CD4-independent-HIGH phenotype." (PMID 17645788, 2007). "The majority of reisolates was capable of CD4-independent infection in NP-2/CCR5 cells and could replicate efficiently in macrophages." (PMID 17645788, 2007). "Taken together, in this study we could show that CD4-independent infection of CCR5 expressing cells was a common characteristic of primary SIVsm isolates." (PMID 17645788, 2007). "In our system, we could show that infection of NP-2/CCR5 cells expressing CCR5 with CD4-independent-HIGH isolates resulted in a low level virus production seven days after infection and we could also observe syncytia induction in these cells." (PMID 17645788, 2007). "Infection with a CD4-dependent virus resulted in evolution to CD4-independence in late reisolates, indicating that CD4-dependent use of coreceptors may change in the course of infection." (PMID 17645788, 2007). "Seven patients (15%) displayed both anti-HCMV IgM and anti-HCMV IgG antibodies, indicating a recent or ongoing infection, but the frequency of CD4+CD28null T cells in the circulation and synovial fluid was similar to IgG-seropositive patients lacking IgM (data not shown)." (PMID 17825098, 2007). "Depending whether isolated early or late in infection, two phenotypes of CD4-independent use of CCR5 could be observed." (PMID 17645788, 2007). "However, there are some correlative findings about the role of strong CD4 T cell help and neutralizing antibodies in human persistent prone infections." (PMID 18000535, 2007). "However, infection of cells expressing CCR5 together with CD4 was at all times more effective than infection of cells expressing only CCR5." (PMID 17645788, 2007). "The few CD4+CD28null T cells found in the joint could instead be a consequence of general patrolling initiated by infection in other tissues." (PMID 17825098, 2007). "In contrast, the VP2 and VP2121‐130 transgenic mice showed decreases in the percent of CD8+ cells infiltrating the brain (20 ± 2.1% and 15 ± 0.7% respectively) and increases in the percent of CD4+ cells (43 ± 5.7% and 43 ± 5.1% respectively) after 7 days of infection with TMEV." (PMID 17388949, 2007). "Isolates obtained early in infection were often of CD4-independent-HIGH-phenotype." (PMID 17645788, 2007).
infection (continued). "In untreated patients, the de novo infection of resting CD4+ T cells is insured by the HIV-1 production from activated infected CD4+ T cells, which leads to the continual replenishing of the pool of infected resting CD4+ T lymphocytes harboring unintegrated HIV-1 DNA." (PMID 17727722, 2007). "CD4-independence is more pronounced early in infection than late." (PMID 17645788, 2007). "Late isolates, especially from LTNP macaques, were more restricted in CD4-independent infections." (PMID 17645788, 2007). "It has been hypothesized that viral uncoating might be the main rate-limiting step for infection of quiescent CD4+ T cells and indeed cellular extracts from activated, but not resting, CD4+ T cells promote uncoating of HIV-1 cores." (PMID 17845727, 2007). "Experimental infection of CD4+ T cells with HTLV-I was known to progressively downregulate CD3 genes transcripts, eventually leading to a CD3- surface phenotype after 200 days of in vitro infection; however, the sequence of CD3 genes loss of expression had not been investigated." (PMID 17822534, 2007). "After the development of Highly Active Anti-Retroviral Therapy (HAART), it became clear that HIV-1 infection was a highly dynamic process involving massive covert replication of HIV-1 in lymphoid tissues at all stages of an infection with continual destruction and regeneration of CD4+ lymphocytes." (PMID 17945027, 2007). "Dixit and Perelson consider the expected inhibition of multiple infections by CD4 down-modulation and identify conditions under which the observed scaling relationship may hold." (PMID 17967052, 2007). "However, variants of HIV with truncated Env are rarely isolated from infected patients, even though HIV-1 infected patients can harbor viruses with truncated Env that are able to mediate CD4-independent infection of CD8+ cells." (PMID 18081926, 2007). "In contrast, CD4+ cells exhibited a down-regulated TLR9 as a consequence of infection." (PMID 16504163, 2006). "However, when the HIV-1 was incubated with media instead (as control), 100% infection of the CD4+ CEM SS cells was detected." (PMID 17125499, 2006). "Later in infection, proviral DNA can be isolated from both naïve and memory CD4+ T cells." (PMID 16916447, 2006). "While 100% of viral replication or infection of the CD4+ CEM SS cells was detected with the filtrate of the control (HIV-1 plus media), no HIV-1 replication or infection of the CD4+ CEM SS cells was detected when the filtrates from the three mixtures were used." (PMID 17125499, 2006). "This, in turn, could contribute to establishment of latent proviral infection in CD4+ memory T cells." (PMID 17176473, 2006). "However, for HIV-1, transport to lymph nodes has the unfortunate side effect of presenting the virus to primary CD4+ T cell targets, facilitating trans-infection and virus dissemination throughout the body." (PMID 16817962, 2006). "To determine whether resistance to infection was transient or persistent, we tested primary CD4 T cells or PBMC obtained from the five EUs at various times during 2–6 years of follow-up." (PMID 17092330, 2006). "Since most of these cells reside in the intestinal tract, profound CD4+ T cell depletion occurs in the intestine within days of infection, whereas peripheral lymphoid tissues such as blood and lymph nodes, which harbor mainly naïve CD4+ T cells, are less severely affected." (PMID 17147469, 2006). "Infection of CD4 T cells may also be inhibited by unidentified soluble antiviral factors secreted by CD8 T lymphocytes." (PMID 17092330, 2006). "To investigate whether 2G12 could inhibit DCs transfer to CD4+ T cells, we performed trans-infection experiments using primary immature MDDCs and TZM-BL cells." (PMID 16817962, 2006).
infection (continued). "Persistent depletion of mucosal CD4+ T cells expressing CCR5 and CCR5/CXCR4, the cells that are targeted during acute and early infection, may perhaps be a consequence of HIV-1 associated cytopathicity and/or nonspecific immune activation and apoptosis." (PMID 17147468, 2006). "CD4 T cells from four of the five EU subjects were resistant to HIV-1 R5 infection." (PMID 17092330, 2006). "The CD4+ T-cell counts in most animals declined over the first few weeks post-infection." (PMID 16398928, 2006). "Nevertheless, the failure of optimal CD4+ T-cell expansion and migration during infection clearly results in the abrogation of B-cell expansion and a subsequent absence of antibody production at specific time-points during infection." (PMID 16611373, 2006). "Therefore, stimulating HIV expression from these resting CD4+ T cells would allow the immune system to recognize infected cells and target the infection more efficiently." (PMID 16293194, 2005). "Similarly, 10 in 10,000 HIV infected individuals have a CD4+ T-cell count less than 200 cells/mm3 after 4.5–9 months of infection." (PMID 15743534, 2005). "In both cases, a diminished transitory component of infection may be involved, either because of insufficient CD4 target cells or reduced signals and responses to cell activation." (PMID 16266436, 2005). "Human immunodeficiency virus (HIV) infection of CD4(-) cells has been demonstrated, and this may be an important mechanism for HIV transmission." (PMID 16368003, 2005). "Infection of CD4+ cells decreased in all patients, with three exceeding expectations." (PMID 16293194, 2005). "The CD4+ T lymphocyte is a major target of infection by primate lentiviruses." (PMID 14737186, 2004). "LAG3 deficiency further enhanced the production of interferon-y (IFN-γ), IL-4, and IL-10 by splenic CD4+ T cells in the initial infection phase, which may contribute to the slight suppression of E. multilocularis growth and development observed in the livers of LAG3-knockout mice." (PMID 41680821, 2026). "Analysis of model-derived results show that lung granulomas from asymptomatic mice have a characteristic spatial profile consisting of higher CD4+ and CD8a+ T cell densities, closer B cell proximity to bronchiolar epithelium, and increased T cell-macrophage proximity in asymptomatic M.tb infection." (PMID 41659494, 2026). "To address this, we performed an overnight stimulation with NS3 DENV peptides (matched to the serotype of infection) in the presence of anti-PD-1 and/or anti-PD-L1 blocking antibodies or an isotype control and measured cytokine production and GzmB/perforin production of CD4+ and CD8+ T-cells." (PMID 40595657, 2025). "However, by four weeks post-infection when the numbers of DLD deficient parasites were significantly reduced, the frequency and absolute numbers of PEPCK specific CD4+ T cells in spleens and dLNs of mice infected with DLD deficient L. major were markedly lower than in WT-infected mice." (PMID 40096189, 2025). "However, vaccination following infection and revaccination of hybrid-immune individuals resulted in a robust expansion of both cytotoxic CD4 and CD8 T-cell responses as well as Tfh levels that are likely key to robust affinity maturation and evolution of neutralizing antibody responses." (PMID 40552302, 2025). "Importantly, the frequency of Tem was associated with elevated levels of inflammatory cytokines in the sera (primarily interleukin (IL)-1β and IL-6), suggesting a potential link between the process of inflammation and the fate of CD4 T cells in 17ZR101 infection." (PMID 40096073, 2025). "This could indicate that, after an infection, there is a delay between the establishment of a liver stage-specific CD4+ T cell response and the emergence of a population of memory T cells in the peripheral circulation that is large enough to be detected by our experimental approach." (PMID 39993000, 2025).